RAG1 (recombination activating 1)
Diseases named in the same sentence as RAG1 in open-access papers (continued):
Sharing a sentence is not in itself a finding about the gene and the disease.
glioblastoma (2 papers, 2025). The most malignant astrocytic tumor (WHO grade IV). "A large number of patients with glioblastoma showed medium expression of RAG1 (∼350 patients), while high RAG1 expression was observed in ∼180 samples." (PMID 41362770, 2025). "Our preliminary results with 5 on Rag1 xenografts are encouraging, but comprehensive toxicology, pharmacokinetics, and orthotopic glioblastoma models are necessary to evaluate the therapeutic window and brain delivery." (PMID 41471777, 2025). "This indicates that RAG2 expression is consistently maintained at moderate to high levels in glioblastoma, while RAG1 exhibits both high and medium levels in the majority of the patients." (PMID 41362770, 2025). "In the present study, we have demonstrated the presence of RAG1 and RAG2 expression in multiple glioblastoma cell lines as well as glioblastoma patient samples." (PMID 41362770, 2025). "Western blotting of the pull-down samples showed that both RAG1 and RAG2 were present and remained as a complex within the glioblastoma cell line, U87, as compared to the positive control, Nalm6." (PMID 41362770, 2025). "In the present study, we report that RAG1 and RAG2 are differentially expressed in various glioblastoma cell lines studied and can bind and catalyze recombination between canonical RSS." (PMID 41362770, 2025). "Thus, our results suggest that RAG1 and RAG2 present in glioblastoma cells can interact and bind to DNA containing 12RSS." (PMID 41362770, 2025). "The RNA-seq data analysis from 693 glioblastoma patient samples from the CGGA database showed that the vast majority of tumors expressed medium to high levels of RAG1 and RAG2, with no samples exhibiting simultaneous low expression of the two genes." (PMID 41362770, 2025). "Since RAG1 and RAG2 expression was seen in glioblastoma cell lines, we wondered whether the RAGs can bind to canonical 12RSS DNA and catalyze the V(D)J recombination, as this may explain several genomic rearrangements seen during glioblastoma." (PMID 41362770, 2025). "Taken together, these results highlight a non-random and coordinated expression pattern of RAG1 and RAG2 in glioblastoma, with very few samples displaying low levels of either gene." (PMID 41362770, 2025).
glomerulonephritis (2 papers, 2019 to 2022). A renal disorder characterized by damage in the glomeruli. "Tnip1–/–Rag1–/– mice, which lack mature T cells and B cells, still developed glomerulonephritis, indicating Ly6Clo monocytes are pathogenic and that adaptive immune system responses were not necessary for kidney pathology." (PMID 35371102, 2022). "Surprisingly, and in contrast to our findings in ABIN1[D485N] × RAG2 KO mice, the ABIN1 KO × RAG1 KO mice, which also lack T and B cells, still developed glomerulonephritis." (PMID 31694920, 2019).
hyperlipidemia (2 papers, 2019 to 2022). "We found that sFLT3L administration reduced weight gain in a Rag1-dependent manner, ameliorating hepatomegaly and hyperlipidemia." (PMID 34983945, 2022).
inflammatory bowel disease (2 papers, 2021). A spectrum of small and large bowel inflammatory diseases of unknown etiology. "(J) Tregs (YFP+) from WT and Pgdfl/flFoxp3Cre mice and T effector (CD4+CD45RBhigh) cells were isolated, mixed, and transferred to Rag1-/- mice as inflammatory bowel disease (IBD) model." (PMID 34709178, 2021).
iris disease (2 papers, 2008 to 2014). "To test the necessity of T and B cells for the pigment dispersing iris disease, we utilized B6.Tyrp1bGpnmbR150X mice with a Rag1 mutation." (PMID 18402690, 2008). "We have previously shown that that lack T and B cells does not alter the iris disease by using a Rag1 mutation." (PMID 24678736, 2014). "The iris disease of Rag1 deficient B6.Tyrp1bGpnmbR150X mice is indistinguishable to that of their littermates with a functional Rag1 gene and an intact adaptive immune system." (PMID 18402690, 2008).
ischemic stroke (2 papers, 2022 to 2024). A stroke disorder caused by obstruction of blood flow to the brain, due to thrombotic (local blood clot formation) or embolic (due to a blood clot or other material traveling from another site) event. "Using this model on Rag1−/− mice, which lack T and B cells, provided the first evidence that T cells contribute to infarct progression after ischemic stroke, as the adoptive transfer of T cells in Rag1−/− mice fully restored infarct volumes." (PMID 38433977, 2024).
malignant glioma (2 papers, 2010 to 2016). A grade III or grade IV glioma arising from the central nervous system. "Additionally, we will identify the in vivo role of Th17 cells using IL-17A−/− or Rag1−/− mice with malignant glioma, adoptively transferred CD4+ T cells from IL-17A−/− mice." (PMID 21060663, 2010). "To determine the effect of irradiation, a treatment for malignant glioma, on CXCR4 down regulated GL26-Cit-Sh2CXCR4 cells, we implanted GL26-Cit-NT (N=10) and CXCR4 knock-down GL26-Cit-Sh2CXCR4 cells intracranially into Rag1−/− mice (N=10)." (PMID 27863376, 2016).
osteopetrosis (2 papers, 2007 to 2023). Osteopetrosis, also known as marble bone disease, is a descriptive term that refers to a group of rare, heritable disorders of the skeleton characterized by increased bone density on radiographs. "KΔ75;Rag1-/- double mutant female mice exhibited a more severe osteopetrosis than Dap12-deficient animals but lost their bone mass after ovariectomy, like single mutants." (PMID 17611620, 2007).
Pneumocystis jirovecii pneumonia (2 papers, 2022 to 2024). "In this report, we present a case of missense mutation in the RAG1 gene causing AIHA as the first symptom, followed by CMV infection and severe Pneumocystis jirovecii pneumonia in a 1-year and 4-month-old female in China." (PMID 39720732, 2024).
sarcoma (2 papers, 2011 to 2025). A usually aggressive malignant neoplasm of the soft tissue or bone. "To explore the mechanism of IgG production in sarcoma cells, we investigated the expression of several enzymes, including RAG1, RAG2 and AID." (PMID 21731691, 2011).
Sjögren’s syndrome (2 papers, 2015 to 2022). "Furthermore, it has been reported that patients with systemic lupus erythematodes (SLE), Sjögren’s syndrome, RAG1 and RAG2 deficiency and X-linked immunodysregulation polyendocrinopathy enteropathy (IPEX) can generate type I IFN auto-antibodies." (PMID 35986347, 2022).
Splenomegaly (2 papers, 2012 to 2016). Abnormal increased size of the spleen. "Thus, CB17 SCID mice show a complete different outcome of disease than T and B cell-deficient C57BL/6 RAG1-/- mice that do not show splenomegaly and liver pathology but develop brain inflammation months after R. typhi infection." (PMID 27548618, 2016).
steatosis (2 papers, 2022 to 2025). Increased lipid within the cytoplasm of cells. "To corroborate this at a microscopic level, we next utilized Phasor-FLIM (Fluorescence lifetime imaging microscopy) to characterize hepatic steatosis in both Rag1−/− and Rag1-Tbet DKO mice undergoing IRI." (PMID 35833123, 2022).
uveitis (2 papers, 2020 to 2022). An inflammatory process affecting a part of or the entire uvea. "Uveitis was evaluated by clinical and histopathological scoring, and comparisons were made in WT vs. Nlrp12−/− mice, lymphopenic Rag1−/− mice reconstituted with WT vs. Nlrp12−/− CD4+ T cells, or among bone marrow (BM) chimeric mice." (PMID 35313917, 2022). "After immunization, Rag1−/− and Nod2−/−Rag1−/− recipients developed similar onset and severity of clinical uveitis, though a trend of reduced severity of uveitis was noted in Nod2−/−Rag1−/− recipients." (PMID 33106495, 2020). "Reconstituted Rag1−/− recipients were immunized with IRBP1–20 and the ability of Nlrp12−/− vs. WT CD4+ T cells to expand and trigger uveitis was evaluated." (PMID 35313917, 2022).
vitiligo (2 papers, 2013 to 2015). Generalized well circumscribed patches of leukoderma that are generally distributed over symmetric body locations and is due to autoimmune destruction of melanocytes. "Adoptive transfer of CD4+ T cells from Ag-GILT+/+Tg mice leads to rapid vitiligo in Ag-expressing RAG1-/- recipients with a median onset of five weeks, consistent with previous findings." (PMID 25875653, 2015). "In Ag-expressing GILT-/-RAG1-/-recipients, the median onset of vitiligo is significantly delayed by one week (p<0.01), consistent with a requirement for GILT expression by peripheral APCs for the priming of TRP1-specific T cell responses." (PMID 25875653, 2015). "The source of the increased Treg cells, that are found in GILT−/−RAG1−/−TRP1Tg mice compared to Ag-RAG1−/− TRP1Tg mice and contribute to tolerance and prevention of vitiligo, remains to be determined." (PMID 24409178, 2013). "In GILT−/− compared to GILT-expressing RAG1+/+TRP1Tg mice, the median onset of spontaneous vitiligo is delayed by 7 weeks." (PMID 24409178, 2013). "Ag-RAG1−/−TRP1Tg mice do not develop vitiligo because they do not express the autoantigen recognized by the transgenic T cells, although naïve T cells from these mice cause rapid, severe vitiligo following adoptive transfer into GILT and TRP1-expressing mice." (PMID 24409178, 2013). "Conversely, adoptive transfer of TRP1-specific T cells from Ag+GILT-/-Tg mice failed to induce vitiligo in Ag-expressing RAG1-/- mice with or without GILT." (PMID 25875653, 2015).
abscess (1 paper, 2025). An inflammatory process characterized by the accumulation of pus within a newly formed tissue cavity which is the result of a bacterial, fungal, or parasitic infection or the presence of a foreign body. "For instance, TLR5/Rag1 double knockout (DKO) mice demonstrate severe immune dysregulation compared to their TLR5 knockout (T5-KO) and Rag1 knockout (Rag1-KO) littermates, with frequent lethal infections caused by Pasteurellaceae and increased abscess formation in multiple organs." (PMID 40444793, 2025).
acute T-cell lymphoblastic leukemia (1 paper, 2021). "Combining cDNA microarray and ChIP-seq analysis, we identify Rag1 and Rag2 as novel Notch1 transcriptional targets in acute T-cell lymphoblastic leukemia (T-ALL) cells." (PMID 34322489, 2021).
adrenal autoimmunity (1 paper, 2025). "Beyond common variants, rare variants in immune genes such as RAG1, TNFAIP3 (A20), LAT, and IKZF2 (HELIOS) have been described in autoimmune syndromes that include adrenal autoimmunity." (PMID 41465179, 2025).
Allergy (1 paper, 2025). An allergy is an immune response or reaction to substances that are usually not harmful. "The highest prevalence of allergy was found in patients suffering from genetic disorders caused by variants in DOCK8, CARD11 (AD DN), ARPC1B, and PLCG2, while there were no occurrences of allergy in patients with defects in the LRBA and RAG1 genes." (PMID 41142799, 2025).
aneurysm (1 paper, 2016). Bulging or ballooning in an area of an artery secondary to arterial wall weakening. "Histologically, the trend toward increased aneurysm size and wall thickness in the Rag1 group suggests that lymphocytes may be more involved in aneurysm rupture over formation." (PMID 27416931, 2016).
Atrophy (1 paper, 2018). Any weakening or degeneration, especially through lack of use. "We demonstrated that RAG1-86nt hamsters have splenic and thymic atrophy, with significantly impaired development of both B and T lymphocytes." (PMID 29734775, 2018).
B lymphocytopenia (1 paper, 2021). "CID-G/AI and AS patients with RAG1 deficiency commonly present with autoimmune manifestations, and 26.3% of them show hypergammaglobulinemia despite profound B lymphocytopenia." (PMID 34622798, 2021).
bacteremia (1 paper, 2022). "In keeping with the kinetics of bacteremia in WT, μMT and Rag1-/- mice, bacterial loads in the blood of μMT females at the time point of mating were similar to WT mice, whereas bacteremia in Rag1-/- females was higher than in the other two groups." (PMID 35580143, 2022). "The reduced prevalence of Bartonella bacteremia in 4-5-week-old μMT mice as compared to extracted μMT embryos and an analogous trend in Rag1-/- mice provide independent support for this hypothesis." (PMID 35580143, 2022).
Bartonella infection (1 paper, 2022). "In contrast, Bartonella infection was detected in at least one embryo from 6 out of 6 Rag1-/- litters analyzed, with a total of 22 out of 42 embryos culture-positive." (PMID 35580143, 2022). "Intriguingly, however, immunocompetent heterozygous Rag1+/- and μMT+/- offspring cleared Bartonella infection within 5 to 11 weeks after birth." (PMID 35580143, 2022).
bone cancer (1 paper, 2021). A primary or metastatic malignant neoplasm affecting the bone or articular cartilage. "Notably, bone cancer-induced mechanical and cold allodynia were reduced by DMXAA treatment in both WT and Rag1−/− mice at early stages (d7 and d10), but not at later stages (d14)." (PMID 34315904, 2021).
bone marrow failure (1 paper, 2013). "In addition, miR-146a-deficient lymphocytes were shown to be a major driver of the development of bone marrow failure and myeloproliferative disease, because miR/Rag1 DKO mice showed normal bone marrow cellularity and an attenuated splenomegaly and myeloproliferative phenotype." (PMID 23705069, 2013).
brain infarction (1 paper, 2022). Tissue necrosis in any area of the brain, including the cerebral hemispheres, the cerebellum, and the brain stem. "Importantly and in line with previous published results, we further observed that depletion of NK cells by an anti-NK1.1 antibody (PK136) in WT and Rag1−/− mice diminished brain infarction in the experimental mouse model." (PMID 34105078, 2022).
cardiac hypertrophy (1 paper, 2023). "Further, TGF-β1 −/− and Rag1 −/− double-knockout mice did not develop cardiac hypertrophy induced by subpressor Ang II doses, as was the case for the controls." (PMID 37569619, 2023).
cartilage tumors (1 paper, 2021). "We previously demonstrated that Ptpn11 gene deletion driven by CD4 Cre recombinase leads to cartilage tumors in a T cell independent manner since the phenotype is observed even in RAG-1 absence." (PMID 34625577, 2021).
cerebrotendinous xanthomatosis (1 paper, 2025). Cerebrotendinous xanthomatosis (CTX) is an anomaly of bile acid synthesis characterized by neonatal cholestasis, childhood-onset cataract, adolescent to young adult-onset tendon xanthomata, and brain xanthomata with adult-onset neurologic dysfunction. "Among Rajput caste, seven RGDs were caste-specific including Cerebrotendinous Xanthomatosis, congenital diarrheal syndrome, HSD17B4-related disorder, hypercholesterolemia type B, Menke-Hennekam Syndrome, RAG1-associated disorder and Sjögren-Larsson Syndrome." (PMID 41516090, 2025).
cholangiocarcinoma (1 paper, 2025). A carcinoma that arises from the intrahepatic biliary tree (intrahepatic cholangiocarcinoma) or from the junction, or adjacent to the junction, of the right and left hepatic ducts (hilar cholangiocarcinoma). "This revealed tumor‐specific potential markers, several of which have been previously implicated in tumor biology (e.g., F2RL2 in gynecological cancers, DHCR24 and RAG1 in thymic carcinoma, PTGDS in cholangiocarcinoma)." (PMID 40784724, 2025).
chronic hepatitis (1 paper, 2019). An active inflammatory process affecting the liver for more than six months. "In contrast to the observations in HBs-tg mice, TIGIT blockade failed to increase ALT levels and induce liver injury in HBs-tg Rag1−/− mice, suggesting a critical role of adaptive immunity in mediating TIGIT blockade-induced chronic hepatitis." (PMID 30644386, 2019).
chronic leukemia (1 paper, 2016). A slowly progressing leukemia characterized by a clonal (malignant) proliferation of maturing and mature myeloid cells or mature lymphocytes. "Using Partek Genomics Suite 6.6 we examined the relationship between expression of RUNX1 and RAG1/RAG2 expression in a panel of acute and chronic leukemias from the MILE study (Microarray Innovations in LEukemia), a global microarray study comprising gene expression analysis of > 4000 patients." (PMID 27056890, 2016).
clostridium difficile infection (1 paper, 2019). Symptomatic infection due to the spore-forming bacterium clostridium difficile. "Previous study demonstrated innate lymphoid cells were a critical role against Clostridium difficile infection based on data from Rag1-/- single gene and Rag2/IL2rg-/- double gene mutated mice." (PMID 31134127, 2019).
co-infection (1 paper, 2021). "We find that helminth co-infection enhances Salmonella colonization of the small intestine even in mice which lack IL-4, Stat6, and RAG1, and also in mice lacking eosinophils, and bacterial microbiota-depleted mice." (PMID 33471793, 2021).
complement deficiency (1 paper, 2014). A genetic deficiency of any of the component of the complement system (including the classical, alternative, and terminal pathway components), that can either be acquired or inherited. "In contrast to mice with complement deficiency or B-cell dysfunction, LPS pretreatment did not improve survival in Rag-1 KO mice (0%, N = 0 of 15) when compared to the control group (0%, N = 0 of 8, p = 0.3)." (PMID 24465843, 2014).
cutaneous leishmaniasis (1 paper, 2021). Leishmaniasis affecting the skin. "Notably, blockade of IL-17A in Rag1-/- mice colonized with S. epidermidis before L. major infection significantly reduced the inflammation suggesting that IL-17 production from ILCs is sufficient to drive inflammation in acute phase of cutaneous leishmaniasis." (PMID 34699567, 2021).
cutaneous vasculitis (1 paper, 2024). Inflammation of the blood vessel wall characterized by palpable purpura.
deficiencies (1 paper, 2021). "Therefore, although the underlying genetic immune deficiencies certainly play a role, it can be speculated that the expansion of Proteobacteria in the relative absence of strict anaerobe expansion may contribute to the differing susceptibility of Rag1–/– and NSG mice to infection." (PMID 34445184, 2021).
developmental delay (1 paper, 2022).
dry eye (1 paper, 2023). "In another report, the adoptive transfer of CD4+ T cells from wild-type C57BL/6 mice with dry eye (enriched in Th1 cells) into RAG1-deficient mice induced corneal epithelial apoptosis by a mechanism that involves IFN-γ secretion at the ocular surface." (PMID 37217914, 2023).
edema (1 paper, 2021). An abnormal accumulation of fluid beneath the skin, or in one or more cavities of the body. "Although the lack of protection from IL-33-induced pulmonary edema in Rag1–/– mice argues against a central role for T cells in the acute vasculitic phase, Th2 cells may be critical for the development of the asthmatic and infiltrative phases, whereas ILC2s drive the vasculitic phase." (PMID 33974563, 2021).
emphysema (1 paper, 2025). "We induced emphysema in Rag1-knockout (Rag1KO) mice and examined changes in the Siglec-F+ neutrophil population." (PMID 40461699, 2025).
enteritis (1 paper, 2025). Inflammation of the small intestine. "Twelve-week-old A20ZF7Rag1–/– mice exhibited negligible intestinal inflammation and expressed levels of Il1b and Ccl20 similar to those in Rag1–/– mice, suggesting that adaptive lymphocytes are required for enteritis in A20ZF7 mice." (PMID 40892518, 2025). "To assess the relative contributions of T and B cells to enteritis in A20ZF7 mice, we interbred these mice with Rag1–/– and Ighm–/– mice." (PMID 40892518, 2025).